CD44 (CD44 molecule (IN blood group))
Diseases named in the same sentence as CD44 in open-access papers (continued):
Sharing a sentence is not in itself a finding about the gene and the disease.
colorectal cancer (continued). "We analyzed the expression profile of putative tumor-initiating cell markers, such as CD44 and CD133, in Caco-2, HCT116, HT29, SW480, and DLD1 colorectal cancer cell lines using flow cytometry." (PMID 33994850, 2021). "Our findings suggest that the CD44+CD133+ subpopulation from Caco-2 cells was highly enriched in tumorigenic cells and will be useful for investigating the mechanisms leading to human colorectal cancer development." (PMID 33994850, 2021). "The expression level of integrin-α9β1 is greatly up-regulated in human colorectal cancer samples and is also increased in the CD133+/CD44+ subpopulation of SW480 cells compared with the CD133-/CD44- subpopulation." (PMID 33790909, 2021). "Twist1 induced EMT and CD44 via AKT/GSK-3β/β-catenin and AKT/NF-kappaB pathways in microsatellite-stable (MSS) cells, while only the β-catenin pathway was activated in MSI colorectal cancer cells." (PMID 34884696, 2021). "Proteins have been proposed as colorectal cancer stem cell markers, including CD133, CD44, ALDH1A1, LGR5 and several others, and these proteins are considered prognostic indicators of CRC." (PMID 34148069, 2021). "Indeed, EpCAM, CD166 and CD44 were more robust as markers of colorectal carcinoma (CRC) CSCs than CD133 alone." (PMID 34774101, 2021). "More importantly, we found that the expression of USP38 was negatively correlated with the expression of CD133, CD44, and SOX2 suggesting that USP38 negatively regulates cancer stem cells in colorectal cancer patients." (PMID 32404892, 2020). "This compound inhibited the expression of various Wnt target genes (such as MYC, AXIN2, and CD44) through conformational modification of TNIK and abrogated the stemness of colorectal cancer cells." (PMID 32429395, 2020). "Using cell sorting, colorectal cancer cells representing five combinations of high/low levels of the markers LGR5, CD44, and EpCAM were isolated and examined for TIC properties and expression of EMT/TIC-related genes." (PMID 31661927, 2019). "This study investigated the co-expression and prognostic significance of the CSCs biomarkers CD44 and CD133 with wild-type EGFR (wtEGFR) and EGFRvIII in colorectal cancer (CRC)." (PMID 30899442, 2019). "MTF (10 mM) decreased the ratio of CD44+/CD133+ CSCs, in four colorectal cancer cell lines, whereas in four other colorectal cancer cell lines, MTF did not disturb the number of CSCs." (PMID 30241339, 2018). "The colorectal cancer cells that undergo EMT exhibit properties of EMT and CSCs, such as high expression of Snail, Lgr5, CD133, CD44 and EpCAM." (PMID 30279970, 2018). "Therefore, this CD44 marker may be a potential therapeutic target of colorectal cancer." (PMID 30279970, 2018). "Using the HT29 transplantation model, we assessed the expression of Lgr5, CD44, and CD133, major human colorectal cancer stem cell markers 25, and CK20, a characteristic differentiation marker 26 by sorted Tie1‐positive cancer cells." (PMID 28464467, 2017). "The distribution of CD44+/CD24+ cells in colorectal cancer is under dispute, although it has been demonstrated that between 50 and 68% of patients suffering from colorectal cancers have high level of CD24+ cells." (PMID 28030837, 2017). "The combined biomarkers CD44 and CD24 have been identified as CSC surface markers in breast, prostate, pancreatic, and colorectal cancers." (PMID 27521216, 2016). "Multiple antibodies directed against LGR5 (Sigma-Aldrich, HPA012530; Abgent, AP2745; Abcam, ab75850), CD44 (Abcam, ab41478) and EPHB2 (R&D, AF467) were tested on normal human colon and colorectal cancer tissues." (PMID 26367378, 2015). "Recent advances in colorectal cancer have led to the characterisation of intestinal stem cell markers, including LGR5, EPHB2, and CD44." (PMID 26367378, 2015).
colorectal cancer (continued). "The downregulation of CD44 after treatment with GO-Y031 suggests that curcumin analogs inhibit gastric cancer stem cells and reflect the inhibition of STAT3 and/or CD44 in colorectal cancer stem cells." (PMID 25331984, 2015). "Curcumin and its analogues significantly suppress CSCs both in vitro and in vivo, which can be seen by the reduced expression of CSC markers for colorectal cancer such as ALDH1, CD24, CD133, CD44, and CD166." (PMID 26457069, 2015). "Both CD44 and LGR5 are widely recognized as key regulators of the stem cell phenotype, particularly in colorectal cancer." (PMID 25906747, 2015). "We next isolated CCSCs from human colorectal cancer cell lines, including SW480 cells, LOVO cells, and HCT116 cells by MACS using antibodies against CD44 and CD24." (PMID 24696849, 2014). "In this study, cell surface markers CD44 and CD24 were thus used to select CCSCs from human colorectal cancer cell lines." (PMID 24696849, 2014). "CD133, CD44 and CD24 are three proposed stem cell markers in colorectal cancer, but discouragingly the distribution differs between patients and tumor cell lines." (PMID 24760019, 2014). "Recently, the CD44 signaling pathway, which promotes tumorigenicity in colorectal cancer, was identified between TAM and CD44-positive cancer cells." (PMID 24883329, 2014). "Several colorectal cancer CSC markers have been reported to date, including CD133, CD44, CD24, CD166, and Lgr-5." (PMID 25396735, 2014). "Apart from CD44 expression, CD24+ cells are also reported to act as cancer stem cells in ovarian and colorectal cancers." (PMID 22693526, 2012). "Beta-catenin, as a transcription factor complexed with TCF4, is known to upregulate expression of many relevant proteins in colorectal cancer, such as c-myc, cyclin D1, LEF-1, CD44, and c-jun." (PMID 22682314, 2012). "In the case of colorectal cancer stem cells (CCSC) at present the best characterized “stem cell” markers are the surface antigens CD133 CD166, CD44 and CD24 (." (PMID 21829496, 2011). "CD44, CD133 and CD166 are adhesion molecules expressed on intestinal stem cells and colorectal cancer stem cells and therefore can be expected to have overlapping expression patterns to LGR5." (PMID 21829496, 2011). "These markers include CD34+CD38- in the case of acute myeloid leukemia, CD44+CD24lowESA- in breast and pancreatic cancer, CD133+ in brain tumors and colon cancer, CD44+ in head and neck cancer and EpCAMhighCD44+CD166+ in colorectal cancer." (PMID 21190562, 2010). "CD44 upregulation has been reported in various invasive tumours and have previously demonstrated that CD44 activation leads to enhanced MMP expression and increased cell invasion in colorectal cancer." (PMID 16552434, 2006). "Additionally, high expression of CD44, CD24, and ALDH1 have been identified as specific markers for identifying, isolating, and tracking human colonic CSCs during the development of colorectal cancer." (PMID 38787133, 2024). "CD44, CD24, and ALDH1 are hypothesized to be specific markers for the identification, isolation, and monitoring of human colon CSCs during colorectal cancer development." (PMID 38787133, 2024). "In colorectal cancer, the specific collaboration of MET with CD44 suggests that targeting the MET-CD44v interaction could be a promising therapeutic strategy to mitigate the tumorigenic effects of MET signaling." (PMID 39769452, 2024). "CD44, CD133, c-Myc, Nanog, OCT4 and SOX2 were known to mark colorectal cancer stem cell properties." (PMID 37083591, 2023). "Both CD44 and LGR5 are involved in local and liver metastasis in colorectal cancer." (PMID 36831488, 2023). "Many authors found that cancer stem cells expressing CD44 in lung cancer tissues, breast and colorectal cancer cell lines have high expressions of PD-L1 on their surface compared to CD44 negative populations." (PMID 36604635, 2023). "CD44 and CD133 were increased during the EMT of colorectal cancer cells." (PMID 37083591, 2023).
colorectal cancer (continued). "CD44 and CD133 are stem cell markers in colorectal cancer (CRC)." (PMID 37098074, 2023). "Importantly, CD44 is an established cancer stem cell (CSC) marker in several tumor types; for example, the CD44 and CD271 in human head and neck squamous cancer cells and the CD44 and CD133 in colorectal cancer cells." (PMID 37894408, 2023). "Genistein consistently reduced the expression of CD133, CD44, and β-catenin in 1,2-dimethylhydrazine (DMH)-induced colorectal cancer in rats, suggesting that genistein might inhibit DMH-induced colon cancer stem cells (CSCs)." (PMID 37298797, 2023). "CD44, CD133, c-Myc, Nanog, and OCT4 were known to mark colorectal cancer stem cell properties." (PMID 37083591, 2023). "Furthermore, CD44 was also demonstrated to enhance epithelial-mesenchymal transition (EMT), which mediates invasion and metastasis in colorectal cancer cells." (PMID 35590122, 2022). "Moreover, the correlation between CD44 and PAK1 activation was reported before in colorectal cancer, where PAK1 activation correlated to CD44 expression levels and promoted chemoresistance." (PMID 35853934, 2022). "Hence, we call for further future research and investigations to be conducted for the purpose of identifying the most effective treatments that specifically target CD44 and CD133 in colorectal cancer." (PMID 36415383, 2022). "Briefly, Rg3 repressed the cancer stemness in both colorectal cancer (LoVo, SW620, HCT116) and liver cancer cells (HepG2, MHCC-97L) via reductions in CD24, CD44, and the epithelial cell adhesion molecule (EpCAM) and activation of ARHGAP9, a tumor suppressor gene." (PMID 36012338, 2022). "Moreover, the gene expression of other CSC surface markers such as CD44, EpCaM, and CD34 was also found to be regulated by promoter DNA hypermethylation in colorectal cancer." (PMID 36498950, 2022). "It has been reported that CD44+ colorectal cancer cells were able to secrete more exosomes than CD44- cells without affecting the miRNA contents." (PMID 36109501, 2022). "In the present study, using MRI, we determined the correlation between glutamine uptake and the distribution of glutamine transporters, namely ASCT2 and SLC38A2 (SNAT2), glutaminase (GLS), and CSC markers, such as CD44 and CD166, in a mouse xenograft model of HT29 human colorectal cancer cells." (PMID 35365739, 2022). "Our findings demonstrate that bufalin can significantly inhibit colorectal cancer stemness and tumorigenesis, which is accompanied by its activity against EMT markers (Slug, ZEB1, N-Cadherin) and functional stem cell markers (CD44, CD133, LGR5, ALDH, and pluripotency factors)." (PMID 36362141, 2022). "In colorectal cancer, MSI1 promotes the development of CD44 cancer stem cells." (PMID 34604242, 2021). "Stemness markers reported for colorectal cancer stem cells include CD133, CD44, LGR5 and ALDH1A1." (PMID 34148069, 2021). "We also investigated co-expression of CD44 and CD133 markers in colorectal cancer cell lines." (PMID 33994850, 2021). "We analyzed the correlation between stemness markers and cholesterol biosynthesis genes in TCGA colorectal cancer (COADREAD) cohort and revealed positive correlations between CSC markers (EphB2 and CD44) and cholesterol biosynthesis genes (HMGCR, HMGCS1, FDPS, and FDFT1)." (PMID 34621019, 2021). "CD133, CD44, and SOX2 are widely considered to be markers of colorectal cancer stem cells." (PMID 34573091, 2021). "For example, the mRNA level of SLC15A4 is increased in the majority of colorectal cancers, and the detection of SLC15A4 and CD44 in feces may help to identify initial CRC cells." (PMID 34168674, 2021). "Mechanistically, PCGF1 promotes the expression of the colorectal cancer stemness markers CD133, CD44 and ALDH1A1 by maintaining histone H3K4me3 and removing histone H3K27me3 marks by increasing the expression of the H3K4me3 methyltransferase KMT2A and the H3K27me3 demethylase KDM6A." (PMID 34148069, 2021).
colorectal cancer (continued). "Given the evidence that SOX2 was aberrantly expressed and involved in the maintenance of CSCs in colorectal cancer, these results indicated the possibility of a functional relationship between SOX2 expression and CD44-mediated CSC property in radioresistant cells upon radiation exposure." (PMID 33445526, 2021). "Upon irradiation, the overexpression of SOX2 facilitated the acquisition of the properties of colorectal CSCs in radiosensitive colorectal cancer cells (SW480 and LoVo) due to an increase in CD44+ population, cell survival, migration, invasion, and tumoursphere-formation." (PMID 33445526, 2021). "Interestingly, both the knockdown and overexpression of SOX2 led to increase in CD44+ population and induction of CSC properties in colorectal cancer following irradiation." (PMID 33445526, 2021). "By comparative analysis of radiation-induced population of CSCs in both radioresistant and radiosensitive colorectal cancer cells, we found that radioresistant cells such as HCT116 and DLD1 specifically increased the CD44+ population after irradiation, which is one of the properties of CSCs." (PMID 33445526, 2021). "For example, the interaction of PKM2 with CD44 suppresses the activity of PKM2 by increasing its phosphorylation at threonine 105, with high production of ROS, thereby increasing cisplatin-sensitivity in colorectal cancer cells." (PMID 32195169, 2020). "Moreover, ablation of CD44 rewires aerobic glycolysis into the TCA cycle, and production of ROS is increased, which in turn increases the cisplatin-sensitivity of colorectal cancer cells (CRC)." (PMID 32195169, 2020). "CD44 is the most commonly used marker of CSCs, with the potential to act as a determinant against the invasion and migration of CSCs and as the key factor in epithelial–mesenchymal transition (EMT)-like changes that occur in colorectal cancer (CRC)." (PMID 33071648, 2020). "The remaining investigated CSC markers (DCLK1, ANXA2, and CD44) did not demonstrate a statistically significant relationship with tested clinicopathological features of colorectal cancer." (PMID 32671503, 2020). "In this study, we investigated whether the expression of CD44 and CD133 in human colorectal cancer cells (HCT8) differently contributed to drug resistance." (PMID 32849878, 2020). "CD44 is extensively used as a TIC marker for prostate, pancreas and colorectal cancers." (PMID 31470802, 2019). "The results showed that the tumorigenic capacity was significantly reduced, the sphere-forming efficiency was decreased and the ratio of CD44+CD24+ cells and the number of colospheres were also obviously reduced in colorectal cancer cells after overexpression of RORβ." (PMID 28137278, 2017). "CD133, CD44, and ALDHA1 were considered as the CSC markers in colorectal cancer." (PMID 28587207, 2017). "CD133, CD44, ALDHA1, Oct-4, and Nanog were reported to be the key CSC markers in colorectal cancer." (PMID 28587207, 2017). "In addition, the expression and co-expression of CD133, CD44, CD54 and CD26 were also examined in the cells suspension derived from fresh tissue of colorectal cancer and liver metastases." (PMID 27764803, 2016). "Even though, the present result is consistent with our previous finding in colorectal cancer initiating cells, the markers CD44 and CD54 have not yet been used to detect and isolate CTCs." (PMID 27764803, 2016). "Also, knockdown of CD44 strongly prevented clonal formation and inhibited tumorigenicity in a xenograft model, concluding that CD44 had a potential to be a CSC marker for colorectal cancer (CRC)." (PMID 27200096, 2016). "In the Pitule's study, no relation was found between CD44 expression and OS of colorectal cancer patients." (PMID 27323782, 2016).
colorectal cancer (continued). "The combination of CD166/CD44 was previously used to identify CSCs from colorectal cancer cell lines; CD166+/CD44+ cells were found to have higher clonogenicity and accelerated tumour development compared to CD166−/CD44− cells, and the observation was cell dependent." (PMID 25881239, 2015). "Recent clinical studies have shown high levels of CD44 expression in gastric cancer, colorectal cancer, and nonsmall cell lung cancer." (PMID 26666511, 2015). "Targeting CD44+ and CD133+ cancer cells or pathways involving a CD133+CD44+ cell subpopulation might be a strategy for colorectal cancer therapy." (PMID 26566931, 2015). "Moreover, CD44, CD133, CD166‚ and EpCAM are considered markers of CSCs in colorectal cancer, and their expression is increased in ampullary carcinoma as compared with ampullary adenoma or normal mucosa." (PMID 26572077, 2015). "We then determined whether salinomycin effectively reduced the expression of the main proposed markers of colorectal cancers stem cells, LGR5, CD133, CD44 and ALDH." (PMID 25565667, 2015). "The colorectal cancer cell line Caco2 has previously been demonstrated to contain a subpopulation of CSCs with tumor initiating capacity characterized by expression of the CD133 and CD44 surface markers when grown in serum containing media." (PMID 24960044, 2014). "Although both CD44 and CD133 were reported as putative markers for many cancer-specific CICs, including colorectal cancer, it is still unclear whether they are of equal functional importance." (PMID 24921652, 2014). "In addition to CD133 and EpCAM, distinct cell surface markers (including CD44 and CD26) help delineate tumor-initiating CSCs in colorectal cancer tissues." (PMID 23826249, 2013). "In a previous immunohistochemical study on colorectal cancer from the several potential CSC markers (ABCG5, ALDH1, CD24, CD44, CD90, CD133, EpCam) that have been proposed for solid tumors, only ABCG5 expression in tumor budding cell was found to be associated with poor survival of the patients." (PMID 23316479, 2012). "Furthermore, our results showed co-expression of CD44 and Musashi-1 (r=0.265, P<0.05), similar to the co-expression of these PSC markers reported in colorectal cancer." (PMID 21829201, 2011). "CD44 expression was higher in the mouse lung carcinoma cell line A2C12, which was isolated from c-myc and c-raf transgenic mice, than in the human lung carcinoma cell line A549 and the human colorectal carcinoma cell line Caco-2." (PMID 19002182, 2008). "Although CD44+CD133+ colorectal cancer stem cell-based spheroids did not exhibit notably increased size compared with the unsorted cell-based spheroids, the cell viability response to 5-FU was higher in CD44+CD133+ sorted spheroid cells than in control spheroid cells." (PMID 39518936, 2024). "Since miRNA-638 has been reported to be down-regulated to promote apoptosis and autophagy by Rh2 in several cancer cell types, other miRNAs may also be involved in the development of colorectal cancers, such as TGFBR1:miR-532-5P, SMAD7:miR-375, PI3KCA:miR-520a, and CD44:miR-509-3P." (PMID 37764996, 2023). "HNRNPLL, a paralog of HNRNPL, has been demonstrated as a negative regulator of invasion and metastasis of mouse colorectal cancer CMT93 cells, which may be caused in part by its negative regulation of splicing CD44 isoforms containing exon v6." (PMID 38106992, 2023). "Likewise, CD44 expression was higher in non-responders in colorectal carcinoma treated with bevacizumab, with an AUC of 0.64." (PMID 37117249, 2023). "However, the impact of CD44 knockdown on the biological behaviors of CSCs has not been fully understood in colorectal cancer." (PMID 35229451, 2022). "Additionally, exosomes derived from CD133+/CD44+ colorectal cancer cells after being transfected with sh-LINC01315 down-regulated BCL-2, MMP-9, and Vimentin, whereas up-regulated Bax, cleaved caspase-3, and E-cadherin in colorectal cancer cells (P < 0.05)." (PMID 35470736, 2022).